IL10 (interleukin 10)
Diseases named in the same sentence as IL10 in open-access papers (continued):
Sharing a sentence is not in itself a finding about the gene and the disease.
helminth infections (165 papers, 2005 to 2025). "Elevated levels of interleukin (IL)-10, IL-6, and leptin have been associated with helminth infection and leprosy, respectively." (PMID 41239264, 2025). "The induction of IgG4 is heavily reliant on IL-10, as evidenced by its association with high-dose antigen exposure models, acquired natural tolerance, and conditions such as bee venom tolerance and helminth infections." (PMID 40358163, 2025). "The immunological hallmark of helminth infections is their ability to induce Th-2 associated immune responses characterized by the presence of the IL-4, IL-5, IL-9, IL-10, and IL-13." (PMID 35087402, 2021). "Previously, it was noted that a type-2 immune response was responsible to helminth infections, which were usually associated with IL-10, IL-5 and IL-4 secretions." (PMID 32228657, 2020). "This is probably because IL-10 is a key anti-inflammatory cytokine protective against helminth infections that cause inflammation." (PMID 29560020, 2018). "For example, helminthic infections are related to IL-10 production and diminish the risk of allergic disorders and have been shown to induce Tregs in an animal model of allergen challenge, thus preventing development of airway inflammation." (PMID 28589115, 2017). "Helminth infections were strongly associated with eosinophilia and hyper-IgE as well as with a Th2-polarized response (increased levels of IL-13, IL-10, and IL4/IFN-γ ratios and decreased levels of IFN-γ)." (PMID 27882241, 2016). "Balanced immune responses during helminth infections in man are associated with increased regulatory cell types, high IgG4 and elevated IL-10 levels and the latter is thought to control morbidity in human schistosomiasis." (PMID 27152725, 2016). "The induction of Tregs and the associated secretion of IL-10 and TGFβ are events central to the immune responses induced during helminth infection and are also believed to be the principal mechanisms by which helminth parasites modulate autoimmune responses." (PMID 24466007, 2014). "Our data on the role of IL-10 and TGFβ in the helminth infection associated modulation of CD4+ Th1 responses implicate IL-10 as the major player in the down modulation of Th1 responses in active TB, at least in the context of filarial infections." (PMID 25211342, 2014). "Anti-inflammatory cytokines such as IL-4 and IL-10 are associated with helminthiasis and eosinophilia and a limited number of studies have reported the detection ofsuch cytokines in CV disorders." (PMID 25303100, 2014). "We observed a positive association between number of helminth infections and peripheral blood eosinophilia, elevated total IgE, spontaneous production of IL-10 and helminth antigen-stimulated production of Th2 cytokines." (PMID 25410903, 2014). "Human studies investigating the regulatory mechanisms underlying the protective effect of helminth infections on atopy have primarily focused on IL-10." (PMID 22970345, 2012). "In humans, chronic helminth infection is also associated with higher IL-10 production, for example in children harboring gastrointestinal nematodes." (PMID 22795966, 2012). "A novel finding of this study was the association of helminth infection with the frequency of IL-10+CD25+CD71+CD73- B cells, a phenotype that had been previously linked to bee venom tolerance in beekeepers and allergen-specific immunotherapy for house dust mite." (PMID 39312581, 2024). "In addition, helminth infections are also intricately associated with the increased expression of the regulatory cytokines IL-10 and TGF-β." (PMID 36016178, 2022). "Lung damage, blood clots, damage-associated molecular patterns (DAMPS) as a result of helminth infection in the lungs, promotes differentiation of macrophages and release of macrophage-derived growth factors and anti-inflammatory IL-10 and TGF-β that activate Treg." (PMID 33193446, 2020).
helminth infections (continued). "Interestingly, IL-10 is associated with susceptibility of helminth infection or with liver lesions caused by liver inflammation or by helminth infection." (PMID 33042162, 2020). "Studies have highlighted the importance of IL-10 in controlling pathology associated with helminth infections as IL-10 deficient mice suffer higher mortality and/or morbidity, whilst depletion of T regulatory cells in vivo result in increased immune responses and parasite clearance." (PMID 25884706, 2015). "Indeed, patients with multiple sclerosis who have helminthic infection exhibit less severe disease, and such protection appears to be associated with elevated levels of IL-10–producing B cells." (PMID 25546822, 2015). "Moreover, helminth infections were associated with elevated circulating levels of IL-10 in the co-infected individuals, implicating a potential regulatory role for IL-10 in co-infections." (PMID 25211342, 2014). "Although IL-10 was associated with helminth infections, this association was not significant after adjustment for confounders; and IL-13 production was significantly associated only with having three helminth infections." (PMID 25410903, 2014). "Thus, co-existent helminth infection is associated with an IL-10 mediated (for filarial infection) profound inhibition of antigen-specific CD4+ T cell responses as well as protective systemic cytokine responses in active pulmonary TB." (PMID 25211342, 2014). "On the other hand, our findings that late-stage EMF patients display increased IL-4 and IL-10 levels are also consistent with the observed early eosinophilia and helminthic infections in EMF, once this type of infection is usually associated with increased levels of these cytokines." (PMID 25303100, 2014). "Polarized Th-2 immune activation associated with helminthic infection modifies cytokine profiles, whereby anti-inflammatory IL-4, IL-10 and IL-13 protect vessel walls from oxidized LDL-induced monocyte injury in the endothelium, and downregulate fibrinogen synthesis." (PMID 19668697, 2009). "Furthermore, emerging evidence suggests that there is significant genetic component to susceptibility or resistance to STH infection, and that there may IL-10 genetic polymorphisms that protect against helminthic infections." (PMID 25888883, 2015). "In addition, the observed epidemiological association of increased prevalence of helminth infection with a lower ratio of allergic manifestations and autoimmune inflammatory conditions in humans is linked to an attenuated immune response by Tregs and IL-10." (PMID 26248316, 2015). "Finally, helminth infections are strongly associated with an IL-10 dominant regulatory environment that could potentially down modulate antigen - specific responses to third party antigens." (PMID 25211342, 2014). "In chronic helminth infections, there exists a strong regulatory immune element with the proliferation of Tregs and release of anti-inflammatory cytokines such as IL-10 and TGF-β." (PMID 40869321, 2025). "In helminth infections, Treg cells drive an increase in IL-10 levels as a result of macrophage activation through alternative pathways." (PMID 41239264, 2025). "Collectively, these mechanisms demonstrate that chronic helminth infections induce potent immunoregulatory activity mediated by IL-10 and regulatory T cells (Tregs), which suppress Th2 responses and reduce inflammatory pathology." (PMID 41567205, 2025). "Recent studies further confirm that helminth infection induces a Th2/regulatory environment, characterized by increased IL-10 and impaired Th1/Th17 responses, which can compromise anti-mycobacterial immunity." (PMID 41583474, 2025). "For leprosy with helminth infection, the mean IL-10, IL-6, and leptin serum levels were 86.43 pg/ml ± 4.34 pg/ml, 447.42 pg/ml ± 122.15 pg/ml, and 19,272.85 pg/ml ± 4,065.23 pg/ml, respectively." (PMID 41239264, 2025).
helminth infections (continued). "Helminth infections are known to induce a strong type 2 response, but IL-10 has been shown to be necessary for infection persistence and host survival." (PMID 40358163, 2025). "In helminth infections, the activation of alternative pathway macrophages will increase regulatory T cell (Treg) cell secretion, characterized by an increased IL-10 level." (PMID 41239264, 2025). "Leprosy patients with helminth infections have considerably greater serum levels of IL-10 and IL-6, suggesting that helminth infection influences leprosy patients’ immunological responses." (PMID 41239264, 2025). "Interleukin-10 and IL-6 play a role in leprosy patients with helminth co-infections, which indicates that there is an influence of helminth infection on the immune responses of leprosy patients." (PMID 41239264, 2025). "Intestinal tissue damage due to helminth infections will also increase the secretion of IL-10 and IL-6." (PMID 41239264, 2025). "In helminth infections, antigen proteins activate Th2 to stimulate the secretion of IL-4 and IL-13, which will stimulate the secretion of Tregs and IL-10." (PMID 41239264, 2025). "By contrast, helminth infection elicits a dominant Th2-type response, which allows the release of IL-4, IL-5, IL-10, and IL-13, cytokines that counteract the Th1 response and promote anti-inflammatory and tissue repair processes." (PMID 40869321, 2025). "Serum levels of IL-10, IL-6, and leptin are known to be raised in leprosy patients and in helminth infection patients, respectively." (PMID 41239264, 2025). "IL-10 is a key regulatory cytokine in helminth infections, known for its role in modulating excessive immune responses and limiting tissue damage." (PMID 40526709, 2025). "Treatment with rTS‐SUCLA‐β, similar to other helminth infections, induces an elevation in IL‐10 levels, indicating that the immunomodulatory effects of rTS‐SUCLA‐β are mediated through activation of the regulatory pathway within the immune system." (PMID 38888451, 2024). "During helminth infections, eosinophils support type 2 immunity by secreting IL-4, IL-5, IL-10, and IL-13." (PMID 39140728, 2024). "Other investigators have also found significantly increased IL-10 levels in humans with Schistosoma infections, and similar findings have also been demonstrated in other helminth infections, such as Ascaris lumbricoides." (PMID 37243099, 2023). "IL-10 induction enhances Th2 differentiation and downregulates Th1 cytokine responses, thereby promoting worm expulsion in various helminth infections." (PMID 38152278, 2023). "Helminth infection reduces the neutralizing capacity of influenza-specific antibodies via the expansion of CD49b+ LAG3+ Tr1 cells expressing IL-10." (PMID 35113966, 2022). "In vivo blockade of IL-10 signalling during helminth infection resulted in an expansion of IFNγ+ and Tbet+ Th1 cells in the small intestine and a coincident decrease in IL-13, IL-5 and GATA3 expression by intestinal T cells." (PMID 35428872, 2022). "Our data emphasise that such cytokine competition is a key feature of the intestinal immune response during enteric helminth infection, and that IL-10 is a key regulator of this process." (PMID 35428872, 2022). "To investigate the impact of IL-10 on the immune response to intestinal helminth infection, we first assessed the location of IL-10 expression during infection with the enteric roundworm, Heligmosomoides polygyrus." (PMID 35428872, 2022). "When we examined the sources of intestinal IL-10 during helminth infection, our data suggested that multiple cell types are involved." (PMID 35428872, 2022). "Here we show that helminth infection in mice elicits IL-10 expression in both the intestinal lamina propria and the draining mesenteric lymph node, with higher expression in the infected tissue." (PMID 35428872, 2022).
helminth infections (continued). "Together our data indicate that IL-10 signalling promotes Th2 differentiation during helminth infection at least in part by regulating competing Th1 cells in the infected tissue." (PMID 35428872, 2022). "In fact, dust allergy is inversely associated with helminth infection but positively associated with increased levels of IL-33 and TNF-α as well as a reduced IL-10 response." (PMID 34360926, 2021). "It is known that the effect of IL-10 as a key immunoregulator in viral, bacterial, fungal, protozoa, and helminth infections is to ameliorate the overresponse of Th1 cells and CD8+ T cells (which usually results in overproduction of IFN-γ and TNF-γ)." (PMID 34659734, 2021). "On the contrary, helminth infection, also, induces T and B regulatory cells that suppress the immune response through the secretion of IL-10, and transforming growth factor (TGF)-β." (PMID 34413850, 2021). "Pathology of chronic helminth infections are characterized by elevated IL-10 and TGFβ that mediate IgG4 production by B cells." (PMID 33968015, 2021). "In MS patients with helminth infections, there is a compensatory abundance of IL-10-producing B cells through a mechanism that is largely dependent on the Inducible T cell costimulator ligand (ICOSLG)-pathway and not on the CD40, CD80 or CD86 pathways." (PMID 34122439, 2021). "The increased activity of regulatory B cells (Breg) is known to be involved in immunosuppression during helminth infection, which is characterized by inducing IL-10-producing Breg cells." (PMID 32197642, 2020). "IL-10 has been known as one of the mechanisms that contribute to induced regulatory responses induced by helminth infection." (PMID 33044969, 2020). "It has been demonstrated that stimuli such as CSF-1, IL-4, IL-10, TGF-β, IL-13, fungi, and helminth infections favor M2 subpopulation polarization, delivering IL-10 in high concentrations, and IL-12 in low amounts." (PMID 32258161, 2020). "Helminthic infections in a host induces immunoregulatory cytokines (interleukin 10 (IL-10) and transforming growth factor-beta (TGF-B) which stimulate T helper cells 2 for immune response against helminth." (PMID 32565832, 2020). "Among the immunoregulatory cells induced during chronic helminth infection, regulatory T cells (Tregs) producing cytokines such as transforming growth factor β (TGFβ) and interleukin 10 (IL-10) have been well documented." (PMID 32498074, 2020). "Macrophages are known to adopt an alternatively activated phenotype when activated in response to helminth infection through IL-10 production." (PMID 31178861, 2019). "As with most helminth infections, treatment with Ts-AE increased the levels of IL-10 and TGF-β, indicating the immunomodulation of Ts-AE takes place through stimulation of the regulatory pathway of immune system." (PMID 31253164, 2019). "Certainly, helminth infections typically lead to an increased production of IL-10 and Th2 cytokines, such as IL-4, and to the down-regulation of Th1 cytokines." (PMID 30500849, 2018). "Helminth infection modulates host T cell function through multiple factors including induction of Tregs, IL-10/TGF-β regulatory cytokines, PD-1/PD-L, and other co-inhibitory molecules such as LAG-3, BTLA-4, CTLA-4, Tim-3, etc.." (PMID 30093899, 2018). "On the other hand, helminths infections are characterized by a strong Th2 immune response dominated by an up-regulation of counter inflammatory cytokines like IL-10 and TGF-β." (PMID 29560020, 2018). "The role of IL-10 production in the regulatory network induced by helminth infection, including Schistosoma, has been pointed out by many." (PMID 30713536, 2018). "Induction of IL-10 has been proven to be essential in the immunomodulation of host immune system that reduce inflammatory responses to helminth infections and to autoimmune/ inflammatory diseases." (PMID 28482922, 2017).
helminth infections (continued). "Helminth infection promotes increased induction of Treg and/or IL-10 production, leading to suppression of Th1/Th17 immune responses." (PMID 29312343, 2017). "IL-10 by several cell types is upregulated during helminth infection (see also above in Section “Direct Regulation of Macrophage Function by Helminths”)." (PMID 29312343, 2017). "In fact helminths are strong inducers of total and parasite-specific IgE despite the high levels of IL-10 produced during chronic helminth infections." (PMID 28350867, 2017). "By contrast, helminth infections typically direct the immune system toward a type 2 response, characterized by high levels of the cytokines IL-4 and IL-10, which can antagonize IFNγ production and its biological effects." (PMID 29312343, 2017). "During helminth infections, there is a predominant Th2 response characterized by a high production of IL-4, IL-5, IL-9, IL-10 and IL-13 cytokines." (PMID 27783986, 2016). "Though the focus on this immunomodulation during helminth infections has been on IL-10, yet contributions of natural T regulatory cells (nTregs) appear to be significant in this context of our study." (PMID 27861499, 2016). "High numbers of functional IL-10 producing Breg cells were also found in patients with multiple sclerosis protected from relapse after acquiring intestinal helminth infection compared with otherwise comparable uninfected patients." (PMID 27476889, 2016). "IL-10 producing Th9 cells have also been shown to play an important role in immunity against intestinal helminth infections." (PMID 26417443, 2015). "In helminth infections, macrophages are an important source of IL-10; however, the molecular mechanism underpinning production of IL-10 by these cells is poorly characterized." (PMID 26116503, 2015). "We also recently reported that albendazole treatment of TB patients with helminth infection compared to placebo leads to a reduced level of eosinophilia and IL-10." (PMID 26248316, 2015). "It has been demonstrated that stimuli such as CSF-1, IL-4, IL-10, TGF-β, and IL-13, fungi and helminth infections, favor M2 subpopulation polarization, delivering IL-10 in high concentrations, and IL-12 in low amounts." (PMID 26074923, 2015). "The effect on spontaneous IL-10 production was greater with increasing number of helminth infections." (PMID 25410903, 2014). "A differential stimulation of IgG4 is promoted by IL-10 which is formed at high concentrations during chronic helminth infections." (PMID 25133189, 2014). "The IL-10 dominated regulatory environment induced in chronic helminth infections is known to modulate the entire repertoire of CD4+ and CD8+ T cell effector functions." (PMID 24699268, 2014). "IL-10 is a powerful immune-regulatory cytokine known to be induced in a variety of helminth infections." (PMID 24699268, 2014). "Our data further showed up-regulation of IL-10 in co-infected WT mice, indicating that helminth infection acts on a MyD88-dependent mechanism of colonic IL-10 response." (PMID 25010669, 2014). "In fact, we have observed previously, in this study population, an increased frequency of the production of IL-10 spontaneously among the children living in conditions of poor hygiene and with intestinal helminth infections." (PMID 25410903, 2014). "The other major mechanism by which helminth infections are known to alter immune responses to bystander antigens is by the production of immuno-modulatory cytokines - IL-10 and TGFβ." (PMID 25211342, 2014). "TGF-B1 is important in the regulation of immune responses and plays, together with IL-10, a central role in minimizing pathology and enhancing tissue repair during helminth infections." (PMID 24397290, 2014). "Larson and colleagues have shown that in mice the suppression of basophil responsiveness by chronic helminth infections was found to be dependent on host IL-10." (PMID 25133189, 2014).